PCSK9 (proprotein convertase subtilisin/kexin type 9)
Diseases named in the same sentence as PCSK9 in open-access papers (continued):
Sharing a sentence is not in itself a finding about the gene and the disease.
endothelial dysfunction (continued). "Despite the emerging role of PCSK9 in ASCVD, there is lack of robust clinical data investigating the interplay of PCSK9 with markers of inflammation, oxidative stress, and endothelial dysfunction in high-risk patients such as CKD patients." (PMID 34336112, 2021). "This study shows that in nondialysis CKD patients, plasma levels of PCSK9 are directly associated with the endothelial dysfunction biomarker sICAM-1 and with Lp(a), an established risk factor for myocardial infraction and cardiovascular death in CKD patients." (PMID 34336112, 2021). "In this clinical study, for the first time, we tested the possible association of PCSK9 levels with inflammation, oxidative stress, and endothelial dysfunction biomarkers in a cohort of CKD nondialysis patients." (PMID 34336112, 2021). "PCSK9 is also associated with increased oxidized LDL-induced apoptosis of human endothelial cells, which may lead to endothelial dysfunction and rupture of a thin-cap fibroatheroma lesion." (PMID 30816133, 2019). "PCSK9 inhibitors might contribute to improve endothelial dysfunction-induced by low shear stress." (PMID 39314624, 2024). "The lack of significant correlation of serum PCSK9 with endothelial dysfunction markers is consistent with our previous report where we noted a weak association between serum PCSK9 concentrations and the risk of complicated course in children with septic shock." (PMID 37365661, 2023). "In-vivo deletion of PCSK9 in PCSK9-/- mice also significantly reduced SA-β-gal activity in aged ECs and the aortic arch, whereas treatment of aged mice with recombinant PCSK9 accentuated SA-β-gal activity in this vessel that is prone to disturbed flow accompanied by endothelial dysfunction." (PMID 37284459, 2023). "However, despite the existence of molecular mechanisms indicating the direct participation of PCSK9 in endothelial dysfunction and arterial inflammation, a large set of previous clinical trials have found no change in systemic inflammatory markers after PCSK9i therapy." (PMID 35933413, 2022). "Proprotein convertase subtilisin/kexin type 9 (PCSK9) is a key protein in lipid metabolism that is also involved in the production of inflammatory cytokines, endothelial dysfunction and aherosclerotic plaque development." (PMID 36768292, 2023). "Furthermore, biomarkers linking oxidative stress and endothelial dysfunction (MDA, ox-LDL, PCSK9) showed significant reduction, after the 4-week supplement administration to the CCAS patients." (PMID 39153251, 2024). "The lack of significant correlation of serum PCSK9 with endothelial dysfunction markers is consistent with our previous report where we noted only a weak association with the risk of complicated course in children with septic shock." (PMID 36778250, 2023). "Serum PCSK9 was not correlated with endothelial dysfunction." (PMID 37365661, 2023). "Serum PCSK9 levels did not correlate with endothelial dysfunction." (PMID 36778250, 2023).
Hypocholesterolemia (41 papers, 2008 to 2025). An decreased concentration of cholesterol in the blood. "With the increasing sophistication of genetic testing methods (e.g., WES and WGS), multiple GOF or LOF mutations in PCSK9 have been found to be associated with hypercholesterolemia or hypocholesterolemia." (PMID 38344397, 2024). "It was subsequently discovered that PCSK9 loss-of-function modifications were clinically significant and cause dominant hypocholesterolemia while reducing CVD risk." (PMID 36835426, 2023). "PCSK9 deficiency has been shown to improve the survival rate of CVD patients, while gain- and loss-of-function mutations in PCSK9 have significant effects on hyper- or hypocholesterolemia in individuals and impact the development of ASCVD." (PMID 37860715, 2023). "PCSK9 loss-of-function modifications show significant clinical importance by causing dominant hypocholesterolemia and lessening the risk of cardiovascular disease (CVD)." (PMID 36835426, 2023). "Loss-of-function variants in PCSK9 have also been described and associated with hypocholesterolemia." (PMID 37138899, 2022). "Our finding that male Pcsk9−/− mice exhibited lowered serum cholesterol levels confirms an earlier report of hypocholesterolemia in Pcsk9 deficient mice." (PMID 35586340, 2022). "In the years that followed, it was also reported that loss-of-function (LOF) variants in PCSK9 were associated with a lifelong state of hypocholesterolemia and a substantial reduction in CVD risk." (PMID 35323658, 2022). "Mice genetically deficient in SEC24A exhibit moderate hypocholesterolemia due to a selective block in PCSK9 secretion from the ER, resulting in an ~50% reduction in plasma PCSK9 levels." (PMID 36193893, 2022). "Recently published clinical evidence also demonstrated that subjects expressing the PCSK9-Q152H variant are healthy, despite a lifelong state of hypocholesterolemia and hepatic ER-PCSK9 accumulation." (PMID 35323658, 2022). "Nonsense, missense and even in-frame deletion mutations have been found in the PCSK9 gene to cause hypocholesterolemia by the increased clearance of LDL-C." (PMID 36552895, 2022). "The clinical benefit of LOF variants in PCSK9 was first described following the sequencing of PCSK9 in African American individuals with hypocholesterolemia from the Dallas Heart Study." (PMID 35323658, 2022). "Several LOF mutations in PCSK9, leading to low plasma PCSK9 levels and consequent hypocholesterolemia, are the cause of impaired processing (e.g., S386A), trafficking (e.g., R46L) or secretion (e.g., S462P)." (PMID 34070931, 2021). "We also sequenced all the exons of the PCSK9 gene in which loss-of-function mutations have been associated with hypocholesterolemia." (PMID 34564380, 2021). "Here, we show that two hypocholesterolemia-associated LOF mutations in the PCSK9 gene can be accurately imputed into large-scale GWAS datasets which raises the possibility of assessing LOFs through genomics-linked medical records." (PMID 24808909, 2014). "Some mutations of PCSK9 cause variable degrees of hypocholesterolemia in homozygous or compound heterozygous carriers." (PMID 21235735, 2011). "Gain- and loss-of-function mutations of PCSK9 may result in hyper- and hypocholesterolemia, respectively." (PMID 26691006, 2015). "In addition, two nonsense and several missense PCSK9 variants were reported that associated with hypocholesterolemia." (PMID 18547436, 2008). "Schisandra chinensis extract (SCE) protects against hypocholesterolemia by inhibiting proprotein convertase subtilisin/kexin 9 (PCSK9) protein stabilization." (PMID 37997262, 2024). "Deletion of hepatic Surf4 results in decreased serum PCSK9 level and profound hypocholesterolemia in mice." (PMID 36193893, 2022). "The action mechanism of PCSK9 is at the basis of the dual effect of its variants, LOF variants causing hypocholesterolemia and GOF variants causing FH." (PMID 29127338, 2017).
Hypocholesterolemia (continued). "Conversely, none of the PCSK9 LOF mutations associated with hypocholesterolemia that we have tested to date displayed enhanced LDL binding." (PMID 36187800, 2022). "Surf4fl/fl Alb-Cre+ mice exhibit normal development, survival and fertility, with marked plasma hypocholesterolemia associated with a hepatic secretion defect for PCSK9 and APOB-containing lipoproteins without evidence for liver injury." (PMID 36193893, 2022). "In another study where PCSK9 nonsense mutations were detected in African subjects, one woman was homozygous for C679X with severe hypocholesterolemia (LDL-C levels of 7 mg/dL) without apparent medical problems." (PMID 34070931, 2021). "A mutation in this binding site could prevent the degradation of the LDL receptor by PCSK9 and also could lead to hypocholesterolemia due to an increase in LDL catabolism." (PMID 21235735, 2011). "However, these PCSK9 hypocholesterolemias appear to be clinically benign." (PMID 21235735, 2011). "For the cases with hypocholesterolemia phenotype, we studied five genes (APOB, PCSK9, MTTP, SAR1B, and ANGPTL3)." (PMID 37138899, 2022). "In conclusion, our study shows that PCSK9 does not play a role in IBD-related inflammation, which is associated with hypocholesterolemia in male but not in female patients." (PMID 40265438, 2025). "Though the mechanisms of these associations have not been finally resolved, this finding excludes a role of PCSK9 in alcoholic cirrhosis related hypocholesterolemia." (PMID 33461570, 2021). "As PCSK9 is primarily produced in the liver, transplantation of SCD marrow into recipient mice should produce SCD mice with no circulating PCSK9 and hypocholesterolemia." (PMID 33020528, 2020).
coronary atherosclerosis (40 papers, 2007 to 2025). Atherosclerosis of the coronary vasculature. "Conversely, PCSK9, which is causal to MI, was similarly inferred to be causal for coronary atherosclerosis." (PMID 40027362, 2024). "Clinical trials have demonstrated that inhibitory monoclonal antibodies of PCSK9 dose-dependently lower LDLc up to 60%, with evidence of both regression and stabilization of coronary atherosclerosis and a reduction in cardiovascular risk." (PMID 36904248, 2023). "Mechanistically, previous studies have proven that after adjusting for ACSVD risk factors (including LDL level), serum PCSK9 levels were linearly associated with the fraction and amount of necrotic core tissue in coronary atherosclerosis." (PMID 36280861, 2022). "For this and other reasons, examination of the effects of PCSK9 variants on the risk of subsequent CHD events in patients with established coronary atherosclerosis is the subject of a separate analysis led by the GENIUS-CHD consortium." (PMID 31664920, 2019). "In recent trials, combination therapies of statins and non-statin agents such as proprotein convertase subtilisin/kexin type 9 (PCSK9) inhibitors (PCSK9i) are proven effective in promoting coronary atherosclerosis regression in patients with moderate-to-high CVD risk." (PMID 37322547, 2023). "In this prospective cohort of patients with FH, we investigated the association of plasma PCSK9 levels with the calcification and stenosis in coronary atherosclerosis and future cardiovascular events under the condition of the era of optimal lipid-lowering therapy." (PMID 31711505, 2019). "The association of PCSK9 with coronary atherosclerosis in contemporary populations may be influenced by a number of factors." (PMID 31672148, 2019). "Since MI occurs on a substrate of coronary atherosclerosis, whether elevated plasma PCSK9 increases MI risk through increased coronary atherosclerosis or by additional mechanisms remains unclear." (PMID 25180781, 2014). "In clinical practice, PCSK9 inhibitors might also be used in selected “primary prevention” patients with multiple risk factors, with statin intolerance syndrome and in patients with evidence of significant coronary atherosclerosis." (PMID 33924893, 2021). "Besides that, PCSK9 has been demonstrated to be expressed in human atherosclerotic plaques and the study investigated the relationship between PCSK9 genotypes/haplotypes and severity of coronary atherosclerosis elucidated a modest association between minimum lumen diameter tertiles and haplotype 3." (PMID 25519174, 2014). "However, it remains unclear whether elevated plasma PCSK9 associates with coronary atherosclerosis (CAD) or more directly with rupture of the plaque causing MI." (PMID 25180781, 2014). "Gene markers associated with coronary atherosclerosis, such as JCAD, GUCY1A3, PCSK9, and SORT1, have demonstrated significant diagnostic and prognostic value in multiple studies." (PMID 39858645, 2025). "Previous studies have underscored the significance of PCSK9 E670G polymorphism and its associated haplotype in influencing LDL cholesterol levels and the severity of coronary atherosclerosis." (PMID 37834124, 2023). "In this study we analyzed the concentration of lipoprotein(a) (Lp(a)), PCSK9-Lp(a) complexes and the circulating monocyte subsets in coronary atherosclerosis." (PMID 37511689, 2023). "In line with this evidence, ATHEROREMO-IVUS study showed that the higher the PCSK9 levels, the higher the necrotic core fraction in coronary atherosclerosis." (PMID 37620933, 2023). "PCSK9 E670G polymorphism is an independent determinant of plasma LDL-C levels, severity of coronary atherosclerosis, and is associated with severity of intracranial atherosclerosis, so can be used as a predictor of large-vessel atherosclerosis." (PMID 36554779, 2022).
coronary atherosclerosis (continued). "This study extends knowledge of the relationships of PCSK9 with glucose and lipid metabolism and coronary atherosclerosis in patients with stable angina and low prevalence of obstructive CAD." (PMID 31672148, 2019). "In conclusion, the present study indicates that higher levels of PCSK9 at baseline were significantly correlated with coronary atherosclerosis." (PMID 31711505, 2019). "In other words, the effect of PCSK9 on MI risk far exceeds its effect on plasma LDL-C levels and on coronary atherosclerosis risk." (PMID 25180781, 2014). "Several studies have shown the effect of PCSK-9 inhibitor on coronary atherosclerosis." (PMID 37217967, 2023). "However, the GLAGOV clinical trial evaluated the effects of PCSK9 inhibition using evolocumab on progression of coronary atherosclerosis." (PMID 36554779, 2022). "Associations were found between the development of aortic valve stenosis in patients with coronary atherosclerosis and certain proteins, such as differential growth factor-15, galectin-4, the Willebrand factor, interleukin 17, transferrin receptor protein 1 and PCSK9." (PMID 34948066, 2021). "The PACMAN AMI (Vascular Effects of Alirocumab in Acute MI-Patients) trial (ClinicalTrials.gov Identifier: NCT03067844) is examining the effects of PCSK9-inhibiting monoclonal antibody, alirocumab on coronary atherosclerosis in acute MI patients via NIRS, IVUS and OCT." (PMID 32695796, 2020). "The main purpose of the present study was to evaluate the interplay of circulating PCSK9 levels with markers of coronary atherosclerosis processes and disease in a contemporary population of patients with stable angina enrolled in the EValuation of INtegrated Cardiac Imaging (EVINCI) study." (PMID 31672148, 2019). "In addition, the ATHEROREMO-IVUS study demonstrated a linear relationship between PCSK9 plasma levels and both fraction and amount of necrotic core tissue in coronary atherosclerosis, independently of serum LDL-cholesterol levels." (PMID 29396513, 2018). "The Lipoprotein Coronary Atherosclerosis Study (LCAS) investigators identified the E670G variation as the most important tagging polymorphism of the PCSK9 gene that acted as an independent determinant of plasma LDL cholesterol levels and coronary atherosclerosis severity." (PMID 17940607, 2007). "Indeed, recent experimental and clinical studies have also reported that higher circulating PCSK9 levels contributed to coronary atherosclerosis by enhancing the expression of pro-inflammatory genes, promoting apoptosis of human endothelial cells and activating platelet reactivity." (PMID 34659352, 2021). "Moreover, recent experimental and clinical studies have also reported that higher circulating PCSK9 level contributed to coronary atherosclerosis via enhancing the expression of pro-inflammatory genes, promoting apoptosis of human endothelial cells and activating platelet reactivity." (PMID 31711505, 2019). "Similarly, most studies exploring the association between plasma PCSK9 and early coronary atherosclerosis demonstrated a not clear direct relationship." (PMID 31672148, 2019). "Evolocumab, a proprotein convertase subtilisin/kexin type-9 inhibitor (PCSK9i), effectively lowers low-density lipoprotein (LDL) and produces favorable changes in coronary atherosclerosis." (PMID 36967822, 2023). "However, our finding that elevated plasma PCSK9 is associated with acute MI, rather than prior MI or with coronary atherosclerosis cautions that the relationship of PCSK9 to MI risk may be more complex than previously thought." (PMID 25180781, 2014). "Low plasma PCSK9 levels are correlated with an unfavorable metabolic profile and diffuse nonobstructive coronary atherosclerosis." (PMID 39040847, 2024). "In particular patients with lower PCSK9 had low HDL cholesterol, a higher CTA score (an integrated measurement of coronary atherosclerosis and risk) and a higher number of non-obstructive and mixed coronary atherosclerotic plaques." (PMID 31672148, 2019).